SAA1 (serum amyloid A1)
Diseases named in the same sentence as SAA1 in open-access papers (continued):
Sharing a sentence is not in itself a finding about the gene and the disease.
endometriosis (2 papers, 2020 to 2025). The growth of functional endometrial tissue in anatomic sites outside the uterine body. "The results of our study indicate that a low expression of SAA1 and SAA2 is associated with an increased risk of endometriosis." (PMID 40450304, 2025). "Meanwhile, our study suggested that higher levels of EPHB4, RSPO3, FSHB, and SEZ6L2 were associated with an increased risk of endometriosis, while lower levels of CD109, SAA1, and SAA2 were also associated with an increased risk of endometriosis." (PMID 40450304, 2025). "This study indicates that the druggable genes EPHB4, CD109, SAA1, SAA2, FSHB, and SEZ6L2 may be associated with the pathogenesis of endometriosis and are potential therapeutic targets for drug treatment." (PMID 40450304, 2025). "CD109, SAA1, SAA2, FSHB, and SEZ6L2 are weakly associated with endometriosis, with higher levels of FSHB and SEZ6L2 correlating with an increased risk of endometriosis, and higher levels of CD109, SAA1, and SAA2 correlating with a decreased risk of endometriosis (PFDR < 0.05, PPH4 < 0.6)." (PMID 40450304, 2025). "We found that the druggable genes EPHB4, CD109, SAA1, SAA2, FSHB, and SEZ6L2 may be associated with the pathogenesis of endometriosis and are potential therapeutic targets for drug treatment." (PMID 40450304, 2025). "CD109, SAA1, SAA2, FSHB, and SEZ6L2 are considered to provide low-level evidence of colocalization with endometriosis (PPH4 ≤ 0.6)." (PMID 40450304, 2025).
hepatitis B (2 papers, 2017 to 2020). "Moreover, compared to patients suffering from hepatitis B and hepatitis C, SAA1 increased more specifically in patients with AIH and a higher level of SAA1 was related with more severe inflammation based on the modified Scheuer histologic scoring system." (PMID 31906950, 2020). "However, the plasma level of SAA1 did not increase in patients suffering from hepatitis B and hepatitis C. We also performed immunochemical analysis to detect SAA1 expression in the liver tissues of patients with AIH." (PMID 31906950, 2020).
hepatocellular carcinoma (2 papers, 2023). A malignant tumor that arises from hepatocytes. "Our novel data in PHH agree with published literature in hepatoma cells, which document a synergy between DEX and various proinflammatory cytokines and LPS in inducing dramatic upregulation of SAA1." (PMID 39619227, 2023).
hyperuricemia (2 papers, 2012 to 2021). An abnormally high level of uric acid. "For example, the genetic polymorphisms in the SAA1 gene was associated with serum uric acid levels, which have a high risk of hyperuricemia." (PMID 34493281, 2021). "The gene for SAA1 is a candidate hyperuricemia gene because it encodes the important inflammation factor SAA." (PMID 22768267, 2012). "The rs12218 SNP in the SAA1 gene was associated with SUA levels in Chinese subjects, indicating that carriers of the T allele of rs12218 have a high risk of hyperuricemia." (PMID 22768267, 2012).
iron deficiency (2 papers, 2014 to 2018). "The results indicate that the lack of hepcidin and not iron deficiency per se accounted for the elevated SAA-1 levels." (PMID 29482530, 2018).
liver fibrosis (2 papers, 2022 to 2024). "Lack of TLR2 in mice inhibits HSC activation, reduces p-JNK and p-p38, and attenuates liver fibrosis induced by CCl4, and SAA1 deficiency substantially reduces p-P38 and p-JNK in the myocardium." (PMID 39105051, 2024). "Hepatic Surf4 deficiency significantly decreased SAA1 secretion from isolated primary hepatocytes, lowered circulating SAA1 levels, and attenuated liver fibrosis in mice receiving CCl4." (PMID 39105051, 2024). "Therefore, we investigated the possibility that Surf4-deficient hepatocytes impaired SAA1 secretion and consequently reduced HSC activation and liver fibrosis." (PMID 39105051, 2024). "Furthermore, our findings indicate that SAA1 secreted by hepatocytes activates HSCs and promotes liver fibrosis in mice." (PMID 39105051, 2024). "Therefore, Surf4 mediates hepatic SAA1 secretion, which activates HSCs and exacerbates liver fibrosis." (PMID 39105051, 2024). "Therefore, hepatic Surf4 facilitates SAA1 secretion, activates HSCs, and aggravates liver fibrosis, suggesting that hepatic Surf4 and SAA1 may serve as treatment targets for liver fibrosis." (PMID 39105051, 2024). "We then investigated whether SAA1 affected liver fibrosis in mice." (PMID 39105051, 2024). "Furthermore, SAA1 knockdown, like hepatic Surf4 deficiency, substantially reduces liver fibrosis in Surf4flox mice, but has no detectable effect on liver fibrosis in Surf4LKO mice, suggesting the contribution of SAA1 to Surf4 deficiency-induced alleviation of liver fibrosis in mice." (PMID 39105051, 2024). "Knockdown of SAA1 significantly decreased liver fibrosis in Surf4flox mice but not in Surf4LKO mice compared with corresponding controls receiving AAV-shRNA NC, as evidenced by Masson’s and Picrosirius red staining (column 1 vs. 2 and column 3 vs. 4)." (PMID 39105051, 2024). "Altogether, these data suggest that Surf4 mediates SAA1 secretion, which may activate HSCs in a paracrine manner via TLR2, thus exacerbating liver fibrosis." (PMID 39105051, 2024). "Do elevated SAA1 levels induce or promote liver fibrosis in young and/or aged mice with no or only mild insult, such as high-fat or high-fructose feeding?" (PMID 39105051, 2024). "Collectively, these findings indicate that knockdown of SAA1 markedly attenuates liver fibrosis in Surf4flox mice but not in Surf4LKO mice." (PMID 39105051, 2024). "Furthermore, knockdown of SAA1 significantly ameliorates liver fibrosis in Surf4flox mice but does not further reduce liver fibrosis in Surf4LKO mice." (PMID 39105051, 2024). "Furthermore, knockdown of SAA1 significantly reduced liver fibrosis in Surf4flox mice but did not further reduce liver fibrosis in Surf4LKO mice." (PMID 39105051, 2024). "Although we noticed an upregulation of select acute phase response (e.g., Saa1, Saa2, and Orm2) and fibrosis genes (e.g., Col1a1 and Timp1) in livers of IXA4-treated DIO mice, IXA4 treatment did not increase liver fibrosis or the levels of multiple plasma cytokines." (PMID 35105890, 2022).
malaria (2 papers, 2022 to 2025). Malaria is a serious and sometimes fatal disease caused by a parasite that commonly infects a certain type of mosquito which feeds on humans. "In contrast to Saa1 and Saa2, the genes Saa3 and Saa4 displayed significantly lower constitutive expressions of about 90 and 178, respectively, and their malaria-responsive expression profiles responded to vaccination, though differently." (PMID 40243929, 2025). "Two important questions are whether SAA1 removal from the circulation could slow down the transition to severe malaria and whether PLTs can secrete stored SAA1 with physiological or pathological consequences in P. vivax malaria." (PMID 34991449, 2022).
pneumonia (2 papers, 2016 to 2024). An acute, acute and chronic, or chronic inflammation focally or diffusely affecting the lung parenchyma, caused by an infection in one or both of the lungs (by bacteria, viruses, fungi, or mycoplasma.). "Altogether, the aggravated loss in body weight, the more pronounced expression of saa1 and the premature mortality pointed to an aggravated course of pneumonia in β5i/LMP7-/- mice especially during the later phase of the disease (48 h post infection)." (PMID 27100179, 2016). "This MR study suggested a potential role of increasing genus Roseburia and family Bifidobacteriaceae abundance, as well as stearidonate (18:4n3), in mitigating inflammation or infectious risks, which could reduce CRP, SAA1, or GlycA levels, pneumonia, or UTI risk." (PMID 38585702, 2024). "The expression of saa1 started at 24 h of infection and increased further over time during the late phase of pneumonia, in both mouse strains, though much stronger and only significant in β5i/LMP7-/- mice." (PMID 27100179, 2016). "After adding other MR models and sensitivity analyses, genus Roseburia was simultaneously associated adversely with CRP (Beta IVW = −0.040) and SAA1 (Beta IVW = −0.280), and family Bifidobacteriaceae was negatively associated with both CRP (Beta IVW = −0.034) and pneumonia risk (Beta IVW = −0.391)." (PMID 38585702, 2024). "After conducting LD analyses and eliminating confounding variables, the ultimate counts of IVs for CRP, SAA1, IL-6, TNF-α, WBC, GlycA, GI, dysentery, pneumonia, BP, BLA, PP, and UTI are 1,594, 1,959, 1,021, 1,911, 1,597, 1,871, 1,870, 1,965, 1,876, 1,875, 1,864, 1,877, and 1,888, respectively." (PMID 38585702, 2024).
pulmonary TB (2 papers, 2020 to 2021). "Quantitative measurements by rapid UCP-LFAs specific for SAA1, IP-10, and IL-6 in serum can be utilized to detect active progressive pulmonary TB in macaques." (PMID 34943175, 2021). "CRP and SAA1 were included in the verification panel because these are considered established major acute-phase effectors and are expected to increase in individuals with pulmonary TB." (PMID 32780727, 2020).
renal fibrosis (2 papers, 2020 to 2024). A final common manifestation of a wide variety of chronic kidney diseases characterized by glomerulosclerosis and tubulointerstitial fibrosis. "In this process, serum amyloid A1 (Saa1) is a gene directly regulated by FABP4 in the MMT process of renal fibrosis." (PMID 39445007, 2024). "Therefore, we next hypothesized that Saa1 may serve as a FABP4 target gene during the process of MMT-mediated renal fibrosis." (PMID 33101287, 2020).
triple-negative breast carcinoma (2 papers, 2022 to 2024). An invasive breast carcinoma which is negative for expression of estrogen receptor (ER), progesterone receptor (PR), and human epidermal growth factor receptor 2 (HER2). "This study explores the role of SAA1 and SAA2 (SAA1/2) in triple-negative breast cancer using a mouse model." (PMID 39336082, 2024). "The overexpression of SAA1 increased the activation of ERK1/2 significantly in the triple-negative breast cancer cell line, MDA-MB-231, following 72-hour transfections." (PMID 36248994, 2022). "In addition, in line with previous literature, the overexpression of SAA1 increased the activation of ERK in the triple-negative breast cancer cell line." (PMID 36248994, 2022). "Furthermore, it has been reported that the ERK1/2 signaling pathway can act to either induce or inhibit autophagy, where this study reported that SAA1 can activate ERK1/2 as an inhibitor of autophagy in triple negative breast cancer cells." (PMID 36248994, 2022). "Therefore, we investigated the role of systemic SAA1 and SAA2 (SAA1/2) in a triple-negative breast cancer mouse model." (PMID 39336082, 2024). "The aim of this study was therefore to investigate the effects of SAA1/2 in an in vivo triple negative breast cancer model (TNBC), in mice lacking both SAA1 and SAA2." (PMID 39336082, 2024).
urinary tract infection (2 papers, 2020 to 2024). "Stearidonate (18:4n3) is a specific omega-3 polyunsaturated fatty acid (PUFA) that is abundant in seafood and is related to reduced SAA1 levels and the risk of urinary tract infection." (PMID 38585702, 2024). "Three metabolites showed similar causal effects on different inflammatory markers or infectious phenotypes, stearidonate (18:4n3) was negatively related to SAA1 and urinary tract infections, and 5-oxoproline contributed to elevated IL-6 and SAA1 levels." (PMID 38585702, 2024). "One of our previous studies showed transiently elevated levels of Saa1/2 in response to urinary tract infection (UTI) and also Saa3 levels after intraperitoneally introduced uropathogenic Escherichia coli in mice." (PMID 32429113, 2020).
adenoma (1 paper, 2023). A neoplasm arising from the epithelium. "Six genes (SAA2, SAA1, CRP, SAA3P, PLA2G2A, and APOA4) listed in the heat map also indicated that the expression of PLA2G2A was limited to the adenoma tissue, following the violin plot results." (PMID 38201587, 2023).
AIDS (1 paper, 2023). A syndrome resulting from the acquired deficiency of cellular immunity caused by the human immunodeficiency virus (HIV). "Genotyping for SAA1 may indeed provide valuable information for the management of patients with poorly controlled hereditary AIDs, allowing treatment decisions to be guided and SAA suppression to be targeted based on risk." (PMID 36991303, 2023).
ankylosing spondylitis (1 paper, 2021). An autoimmune chronic inflammatory disorder characterized by inflammation in the vertebral joints of the spine and sacroiliac joints. "Dysregulation of SAA1, TUBA8 and monocytes are key factors in ankylosing spondylitis with femoral head necrosis." (PMID 35126370, 2021).
autoimmune disease (1 paper, 2013). A disorder resulting from loss of function or tissue destruction of an organ or multiple organs, arising from humoral or cellular immune responses of the individual to their own tissue constituents. "The gene showing the highest level of induction, SAA3, (i.e., 1,180 fold induction) along with SAA1 (i.e., 61 fold, 10th induction) are well-known inflammatory markers in patients with autoimmune disease, chronic infection and cancer." (PMID 24086273, 2013).
B-cell lymphoma (1 paper, 2024). "Additionally, noteworthy genes, including IKZF2, CCL4, SAA1, and CD40, exhibited differential expression in the TCL group compared to the B-cell lymphoma (BCL) group." (PMID 39911484, 2024).
brain inflammation (1 paper, 2021). "Once a positive correlation between SAA1 serum levels and TLR4 mRNA with significant predictive value for severity and patient outcome was established, we explored the role of SAA1 in brain inflammation." (PMID 34070533, 2021).
cerebral infarction (1 paper, 2013). An ischemic condition of the brain, producing a persistent focal neurological deficit in the area of distribution of the cerebral arteries. "In this exploratory study, we investigated the association between genetic polymorphisms of SAA1 and cerebral infarction in a Chinese population." (PMID 23987125, 2013). "In the present study, we performed a case–control study to observe the relationship between SAA1 genetic polymorphism and cerebral infarction." (PMID 23987125, 2013). "In conclusion, the SAA1 genetic polymorphisms were associated with cerebral infarction in a Chinese population." (PMID 23987125, 2013). "In the present study, we found that rs12218 variation in the SAA1 gene was associated with cerebral infarction in a Chinese population." (PMID 23987125, 2013). "Genetic polymorphism of SAA1 may be a genetic maker of cerebral infarction in Chinese." (PMID 23987125, 2013). "The mechanisms which may link SAA1 genetic polymorphism to cerebral infarction are largely unknown." (PMID 23987125, 2013). "The previously reported 4 Single Nucleotide Polymorphisms (rs12218, rs4638289, rs7131332, and rs11603089) of SAA1 gene were genotyped by TaqMan method in a case–control study including 287 cerebral infarction patients and 376 control subjects." (PMID 23987125, 2013).
chronic hepatitis (1 paper, 2020). An active inflammatory process affecting the liver for more than six months. "Using ELISA, the most overexpressed DEP, serum amyloid A 1 (SAA1), was confirmed to be increased specifically in the plasma of patients with AIH compared to other chronic hepatitis." (PMID 31906950, 2020). "However, the role of SAA1 in chronic hepatitis has not yet been clearly elucidated." (PMID 31906950, 2020).
chronic obstructive pulmonary disease (1 paper, 2025). A chronic and progressive lung disorder characterized by the loss of elasticity of the bronchial tree and the air sacs, destruction of the air sacs wall, thickening of the bronchial wall, and mucous accumulation in the bronchial tree. "SAA1 is related to the acute exacerbation of chronic obstructive pulmonary disease, and higher levels of MMP-9 correspond to a higher influx of neutrophils and lymphocytes, signaling an exacerbation of COPD in which a higher burden of MMP-9 is observed in the airways." (PMID 40228208, 2025).
Cirrhosis (1 paper, 2020). A chronic disorder of the liver in which liver tissue becomes scarred and is partially replaced by regenerative nodules and fibrotic tissue resulting in loss of liver function. "Moreover, SAA1 and HP, which were found to be upregulated DEPs in our results, play important roles in the surveillance of HCC in patients with an early stage of cirrhosis." (PMID 31906950, 2020).
Cognitive impairment (1 paper, 2026). Abnormal cognition is characterized by deficits in thinking, reasoning, or remembering. "We identified liver‐derived blood proteins C3, HP, ITIH4, and SAA1 as the candidate molecules associated with cognitive impairment based on the proteomics of mouse liver and blood, as well as the transcriptomic and proteomic profiles of human organs." (PMID 41221556, 2026).
cryptorchidism (1 paper, 2022). The failure of one or both testes of a male fetus to descend from the abdomen into the scrotum during the late part of pregnancy. "Furthermore, there is evidence that cryptorchidism may facilitate the emergence of antisperm antibodies and thus the development of autoimmunoinfertility, as we address here for SAA1 and HLA-DRB1." (PMID 36613967, 2022).
delirium (1 paper, 2023). A disorder characterized by confusion; inattentiveness; disorientation; illusions; hallucinations; agitation; and in some instances autonomic nervous system overactivity. "In addition, the acute phase reaction serum amyloid protein 1 (SAA1) and the C-reactive protein (CRP) seem to be implicated in the pathogenesis of SAD-delirium." (PMID 37958765, 2023).
dementia (1 paper, 2022). Loss of intellectual abilities interfering with an individual's social and occupational functions. "The difference of SAA1 level in CSF might be relative with different dementia symptoms for JE patients, which need to be paid more attention in future research." (PMID 35379280, 2022).
dermatitis (1 paper, 2021). An inflammatory process affecting the skin. "This was probably due to the increased circulating inflammatory cytokines produced from the active dermatitis, which activated circulating inflammatory cells, and SAA1 increased in the plasma." (PMID 35008464, 2021).
dermatomyositis (1 paper, 2026). Dermatomyositis (DM) is a type of idiopathic inflammatory myopathy characterized by evocative skin lesions and symmetrical proximal muscle weakness. "Using LASSO regression, SVM, random forest (RF), GBM, GLM, KNN, and NNET machine learning algorithms, four core genes were identified: SAA1, NACAD, SLC14A1, and MYBPH, all of which were highly expressed in dermatomyositis lesion tissues." (PMID 41911226, 2026).
dilated cardiomyopathy (1 paper, 2022). Cardiomyopathy which is characterized by dilation and contractile dysfunction of the left and right ventricles. "While CXCL9, CXCL10, and CXCL11 belong to the chemokine family, CX3CR1, ADORA3 and SAA1 have not been reported in dilated cardiomyopathy, and further research is needed." (PMID 35618744, 2022).
dysplasia (1 paper, 2020). A usually neoplastic transformation of the cell, associated with altered architectural tissue patterns. "Based on global transcriptomics by RNA sequencing, OLK with dysplasia is different from OLK without dysplasia in terms of its molecular pathology: at least 47 genes were found to be differentially expressed between OLK with and without dysplasia, including SAA1, SAA2, and KRT31." (PMID 33327496, 2020).